SMIM42 (small integral membrane protein 42)
Gene: Protein-coding gene on chromosome 1 (158,127,287 to 158,128,301, reverse strand). Ensembl gene ENSG00000288460.
Subcellular location: Membrane
Gene Ontology:
Cellular component: membrane
Homologues: Orthologues: pig SMIM42 (77% identical).